ZBTB20 (zinc finger and BTB domain containing 20)
Diseases named in the same sentence as ZBTB20 in open-access papers (continued):
Sharing a sentence is not in itself a finding about the gene and the disease.
depression (5 papers, 2014 to 2024). "Two recent studies have reported ZBTB20 variants associated with both major depressive disorder and SAD in a sex-specific manner." (PMID 39766481, 2024). "The ZBTB20 (rs139459337) SNP results in reduced expression of the ZBTB20 gene, which has been associated with seasonal affective disorder and major depressive disorder." (PMID 38132358, 2023). "We show that major depressive disorder is associated with significant hypermethylation within the coding region of ZBTB20, and is replicated in an independent cohort of 356 unrelated case-control individuals." (PMID 24694013, 2014). "Here, we observed that the effects of CRY1, PER3-VNTR, and ZBTB20 were also directly associated with depression, underscoring the possibility that these genes directly impact mood regulation via transcriptional (CRY1, PER3-VNTR) or activational (ZBTB20) regulatory mechanisms." (PMID 38132358, 2023). "Given that depression and abnormal aggression are often comorbid, altered expression of Zbtb20 might underlie the behavioral abnormalities reported in stressed Tph2+/− animals." (PMID 37542675, 2023). "In addition, hypermethylation in the ZBTB20 gene is shown to be associated with major depressive disorders." (PMID 25798087, 2015). "Analysis of brain tissue and expression data in the region also supports a model whereby misexpression of ZBTB20 may be associated with depression." (PMID 24694013, 2014). "ZBTB20 plays an essential role in the specification of the Cornu Ammonis-1 field identity in the developing hippocampus, a region previously implicated in the development of major depressive disorder." (PMID 24694013, 2014). "As a transcription factor, ZBTB20 is also involved in synaptic transmissions, which could influence glucose homeostasis, glucocorticoid stress pathways, or monoamine pathways associated with depression symptoms." (PMID 38132358, 2023). "Additional studies are required to better understand the sex-specific functions of DELEC1 and ZBTB20 in depression and addiction." (PMID 39766481, 2024). "Given this overlap, we utilized patient depression scores (BDI) as the outcome for ARACNE analysis to test the hypothesis that PER3-VNTR, CRY1, and ZBTB20 are directly involved in mood regulation." (PMID 38132358, 2023). "Interestingly, protective effects of CRY1-GG, PER3-VNTR-4,5, and ZBTB20 genotypes on seasonality and depression were not mediated by chronotype, suggesting some clock variants have direct effects on depressive symptoms related to SAD." (PMID 38132358, 2023).
Hepatic steatosis (4 papers, 2015 to 2025). Steatosis is a term used to denote lipid accumulation within hepatocytes. "In ob/ob mice, which exhibit severe obesity and hepatic steatosis due to the leptin deficiency, Zbtb20 expression was substantially increased in the liver at both mRNA and protein levels compared to lean control." (PMID 28327662, 2017). "Considering that hepatic steatosis is closely associated with insulin resistance, we then evaluated the potential role of liver Zbtb20 in HCD-induced insulin resistance." (PMID 28327662, 2017). "ZBTB20 ablation protects against diet-induced liver steatosis and improves hepatic insulin resistance." (PMID 39911797, 2025). "In the present study, we observed that specific deletion of liver Zbtb20 improved HCD-induced hepatic steatosis and insulin resistance." (PMID 28327662, 2017). "Taken together, the findings not only indicate the connection of noncoding ZBTB20 transcripts with hepatic steatosis, but also suggest that the protective effect of BBR against NAFLD is associated with the expression of these lncRNAs." (PMID 25623289, 2015). "Lastly, this study demonstrates that hepatic ZBTB20 may play an important role in the pathophysiology of hepatic steatosis and insulin resistance." (PMID 28327662, 2017). "Finally, we show that Zbtb20 ablation protects from diet-induced liver steatosis and improves hepatic insulin resistance." (PMID 28327662, 2017). "One possibility is that the activity of liver Zbtb20 may be enhanced in the pathogenesis of hepatic steatosis." (PMID 28327662, 2017). "We suggest ZBTB20 is an essential regulator of hepatic lipogenesis and may be a therapeutic target for the treatment of fatty liver disease." (PMID 28327662, 2017). "Our data demonstrate that ZBTB20 is an essential regulator of lipid metabolism, and may serve as a therapeutic target for fatty liver disease." (PMID 28327662, 2017). "To explore the potential role of Zbtb20 in the pathophysiology of NAFLD, we first examined Zbtb20 expression in fatty liver." (PMID 28327662, 2017). "Regarding to its potential role in the pathophysiology of hepatic steatosis, unexpectedly, Zbtb20 expression was not significantly altered in HCD-induced fatty liver at the mRNA or protein levels." (PMID 28327662, 2017).
Intellectual disability (4 papers, 2017 to 2026). "NCAM1 and ZBTB20 are strong candidates for having a role in cognitive aging with mutations in ZBTB20 resulting in intellectual disability, and NCAM1 previously found to be associated with associative memory in humans." (PMID 34285142, 2021).
developmental delay (3 papers, 2017 to 2024). "In lineage 2, risk genes associated with developmental delay, such as ZBTB20 and HNRNPU, were highly expressed at the initial stage." (PMID 39363111, 2024).
Hypoglycemia (3 papers, 2016 to 2018). A decreased concentration of glucose in the blood. "ZBTB20 is a multifunctional protein as ZBTB20-deficient mice exhibit hypoglycemia, growth retardation, and premature lethality." (PMID 29616049, 2018). "The mice lacking Zbtb20 exhibit hypoglycemia, depletion of energy stores, insulin hypersensitivity, growth retardation and premature lethality." (PMID 28327662, 2017).
lung carcinoma (3 papers, 2016 to 2021). "ZBTB20 (also known as DPZF, HOF, and ZNF288), which belongs to the BTB/POZ zinc finger family of proteins, represses forkhead box O1 (FoxO1) expression in lung cancer cells and promotes cell growth." (PMID 27183310, 2016). "Similarly, ZBTB20, a member of the POK family of transcriptional repressors, is upregulated in lung cancer compared to adjacent normal tissue through transcriptional repression of FOXO169." (PMID 34887443, 2021).
Anxiety (2 papers, 2017 to 2023). Intense feelings of nervousness, tension, or panic often arise in response to interpersonal stresses. "ZBTB20 was associated with increased anxiety risk in combinations with CRY2_AG and CRY2_GG and was associated with decreased anxiety risk in combinations with PER3-A_CG and PER3-A_CC." (PMID 38102312, 2023). "In males, the CRY1_CC/PER3-A_GG combination was directly associated with severe anxiety, and ZBTB20 variants occurred in risk combinations with CRY2_AG and PER3-B_GG." (PMID 38102312, 2023). "We describe novel, robust associations between gene combinations involving the ZBTB20 SNP (rs1394593) and risk of anxiety symptoms in a large population sample." (PMID 38102312, 2023). "Our findings provide further support for ZBTB20 as a regulator for circadian clock genes and demonstrate that genotype combinations that include ZBTB20 variants can exhibit sex-specific outcomes on anxiety symptoms." (PMID 38102312, 2023). "In this study, we investigate associations of clinical features and SNP variants in core clock genes, including ZBTB20, with anxiety (Generalized Anxiety Disorder 7-item scale (GAD-7)) scores in a UK Biobank population of 90,882 individuals, aged 40–69 years old." (PMID 38102312, 2023). "Here, we report strong sex-specific associations of circadian gene variants with anxiety symptoms and propose that a variant of ZBTB20 (rs1394593) influences anxiety risk via amplification or attenuation of anxiety symptoms in combination with other clock variants." (PMID 38102312, 2023). "In males, CRY1/PER3-A and PER3-B/ZBTB20 genotype combinations were associated with anxiety risk." (PMID 38102312, 2023). "Zbtb20 directly impacts on the development of different parts of the hippocampus, affecting behavioral traits such as memory and anxiety." (PMID 28125592, 2017). "Loss of ZBTB20 repression activity may lead to increased PER3-B expression and greater circadian disruption, influencing the likelihood of anxiety symptoms." (PMID 38102312, 2023). "The results of the current study suggest that decreases in the transcriptional repression of CRY2 by ZBTB20 may lead to greater transcription of CRY2, which exerts direct effects on anxiety through mood-related pathways." (PMID 38102312, 2023).
cardiac hypertrophy (2 papers, 2020 to 2024). "Additionally, scGO identified genes such as ZBTB20, ESRRG, and SOX6, which have established links to the onset of cardiac hypertrophy." (PMID 39820437, 2024).
cervical cancer (2 papers, 2021 to 2024). A primary or metastatic malignant neoplasm involving the cervix. "Multi-genomic analysis from the Cancer Genome Atlas (TCGA) also identified ZBTB20 as one of ten potential driver genes in cervical cancer." (PMID 38397429, 2024). "Genetically, ZBTB20 is a hotspot of genetic variation or fusion in many cancers including GC, glioma, MB, colorectal cancer, and cervical cancer." (PMID 38397429, 2024).
CNS cancers (2 papers, 2019 to 2024). "Like GC, analyses from human glioma samples have identified the ZBTB20 gene as a hot mutation site." (PMID 38397429, 2024). "MicroRNAs (miRNAs) that target ZBTB20 and the long non-coding RNA (IncRNA) ZBTB20-AS4 are also implicated in the classification and prognosis of patients with low-grade gliomas." (PMID 38397429, 2024). "Moreover for ZBTB20 and PFKFB2 genes plausible link between genes alteration and glioma proliferation and invasion was underlined, especially in the context of glioma-associated cells." (PMID 31170943, 2019).
cognitive deficit (2 papers, 2020 to 2021). "Together, these results suggest that Zbtb20 hypofunction does not significantly contribute to the pathogenesis of cognitive deficits and behavioral abnormalities in hAPP-J20 mice." (PMID 33833046, 2021).
colorectal cancer (2 papers, 2024 to 2026). A primary or metastatic malignant neoplasm that affects the colon or rectum. "Apart from BC, ZBTB20 rs10511330 (intron variant, T > A/C) and rs16822593 (intron variant, G > A) were identified as two of the top ten single nucleotide polymorphisms (SNPs) in a cohort of patients with colorectal cancer." (PMID 38397429, 2024).
myocardial infarction (2 papers, 2020 to 2025). Gross necrosis of the myocardium, as a result of interruption of the blood supply to the area, as in coronary thrombosis. "The level of expression of ZBTB20 correlated with the functional recovery of rat hearts after myocardial infarction." (PMID 41294801, 2025).
schizophrenia (2 papers, 2014 to 2020). A major psychotic disorder characterized by abnormalities in the perception or expression of reality. "Further, LSAMP and ZBTB20 have each been implicated in various brain regions associated with schizophrenia." (PMID 24650298, 2014).
Brachycephaly (1 paper, 2023). An abnormality of skull shape characterized by a decreased anterior-posterior diameter. "The patient exhibited classic phenotypic features, including a high hairline, high-arched palate, and brachycephaly at birth, as well as an absent corpus callosum observed on postnatal MRI and genotypic findings of a pathogenic variant in ZBTB20." (PMID 37927765, 2023).
brain injury (1 paper, 2023). Acute and chronic (see also brain INJURIES, CHRONIC) injuries to the brain, including the cerebral hemispheres, CEREBELLUM, and brain STEM. "Following induced ischemic brain injury, the number of ZBTB20-positive cells increases." (PMID 37760773, 2023). "This supports the hypothesis that ZBTB20 is a regulator of reactive astrogliosis in pathological conditions, including after ischemic brain injury." (PMID 37760773, 2023).
colitis (1 paper, 2024). Inflammation of the colon. "As such, Zbtb20 conditional knockout mice display severe intestinal inflammation and damage in response to induction of acute colitis, whereas adoptive transfer of Zbtb20+ Treg cells, but not non-Zbtb20 Tregs, rescues the mice from colitis." (PMID 38397429, 2024).
dwarfism (1 paper, 2016). "Disruption of Zbtb20 leads to anterior pituitary hypoplasia, hypopituitary dwarfism and a complete loss of mature lactotropes." (PMID 27079169, 2016).
experimental autoimmune encephalomyelitis (1 paper, 2021). An autoimmune demyelinating disease of the central nervous system that is produced experimentally in animals by the injection of homogenized brain or spinal cord in Freund's adjuvant. "Zbtb20 is a transcription factor to promote the differentiation and longevity of plasma cells which suppress the pro-inflammatory response during experimental autoimmune encephalomyelitis and Salmonella infection." (PMID 34594327, 2021).
gestational diabetes (1 paper, 2024). Carbohydrate intolerance first diagnosed during pregnancy. "Lastly, three new loci were significantly associated with gestational diabetes (top SNPs: rs72956265, rs10890563, rs79596863), located on or near ZBTB20, GUCY1A2, and RPL7P20, respectively." (PMID 38714721, 2024).
hemangioma (1 paper, 2011). A benign vascular lesion characterized by the formation of capillary-sized or cavernous vascular channels. "ZBTB20 expression in normal hepatocytes from para-tumoral tissue of hemangiomas of liver and cirrhotic liver were negative or weakly positive, while mainly moderate or strong positive in HCC tumors." (PMID 21702992, 2011).
hepatic (1 paper, 2025). "Second, we discover that the transcriptional repressor Zbtb20 acts as a critical suppressor of Zhx2 expression, forming a regulatory axis that plays a crucial role in liver injury responses and offers a novel molecular insight into hepatic disease progression." (PMID 40589742, 2025).
hyperuricemia (1 paper, 2025). An abnormally high level of uric acid. "Among these, the upregulation of ZBTB20, a transcriptional repressor of the urate transporter ABCG2, may explain the persistent hyperuricemia observed in CGA by impairing renal urate excretion." (PMID 41511324, 2025).
hypopituitarism (1 paper, 2016). A condition of diminution or cessation of secretion of one or more hormones from the anterior pituitary gland. "In this study, we show that ZBTB20 is highly expressed by all the mature endocrine cell types in anterior pituitary, and its deficiency leads to anterior pituitary hypoplasia and hypopituitarism as a result of complete absence of mature lactotropes and impaired expansion of somatotropes." (PMID 27079169, 2016).
hypothyroidism (1 paper, 2018). Abnormally low levels of thyroid hormone. "Mutational clustering in the ZNF region is described for ZBTB20 (OMIM# 606025) as well, where de novo variants in the C2H2 ZNF domain of this protein lead to a hypothyroidism phenotype." (PMID 29573576, 2018).
infarction (1 paper, 2020). A localised pathological necrosis of tissue resulting from obstruction of the blood supply usually by a thrombus, an embolus, or vascular torsion. "This study aims to determine the efficacy of Zinc finger protein ZBTB20 in treatment of post‐infarction cardiac remodelling." (PMID 33063955, 2020).
itch (1 paper, 2021). "The results above suggest that ZBTB20 in primary sensory neurons plays an important role in mediating histamine- and non-histamine-induced itch." (PMID 33748159, 2021). "Finally, silencing endogenous ZBTB20 with recombinant lentivirus expressing a short hairpin RNA against ZBTB20 (LV-shZBTB20) in TG neurons attenuated histamine- and non-histamine-induced itch and downregulated TRP channels in the TG." (PMID 33748159, 2021).
leukemia (1 paper, 2024). A malignant (clonal) hematologic disorder, involving hematopoietic stem cells and characterized by the presence of primitive or atypical myeloid or lymphoid cells in the bone marrow and the blood. "Despite these findings, none of the studies delineate the in vivo effects of ZBTB20 on leukemia progression, nor is it clear whether ZBTB20 is an original cause or just a mediator of other causative factors in leukemias." (PMID 38397429, 2024).
Listeria monocytogenes infection (1 paper, 2024). "However, in Listeria monocytogenes infection, Zbtb20-deficiency improved CD8 T cell memory functions due to efficient use of diverse fuel sources." (PMID 38861581, 2024).
liver dysfunction (1 paper, 2015). "MRAK052686 is located in 3’UTR of protein-coding gene Zbtb20, which is an important regulator of glucose homeostasis and has been reported to associate with liver dysfunction." (PMID 25623289, 2015).
mantle cell lymphoma (1 paper, 2024). Mantle cell lymphoma is a rare form of malignant non-Hodgkin lymphoma affecting B lymphocytes in the lymph nodes in a region called the ``mantle zone''. "Very recently, one group for the first time revealed the roles of ZBTB20 in mantle cell lymphoma (MCL), an aggressive subtype of non-Hodgkin’s lymphomas." (PMID 38397429, 2024).
metastatic tumors (1 paper, 2024). "PFKP (locus: 10p15.2) was positively associated with the development of metastases, whereas the ZBTB20 gene (locus: 3q13.31) was downregulated in the metastatic tumors (p-raw < 0.05)." (PMID 38673877, 2024). "The genes that were upregulated in the monosomy 3/metastatic tumors (PFKP, NUP88) exhibited an average fold change (FC) of 2.06 ± 0.82, whereas the downregulated genes (INSR, RBKS, and ZBTB20) differed by an average of −1.87 ± 0.44-fold." (PMID 38673877, 2024).
mood disorder (1 paper, 2023). A cognitive disorder a disturbance in which the person's mood is hypothesized to be the main underlying feature. "Our findings also support previous findings that the ZBTB20 SNP is an important factor in mood disorders, including seasonal affective disorder." (PMID 38102312, 2023).
non-small cell lung carcinoma (1 paper, 2023). A group of at least three distinct histological types of lung cancer, including non-small cell squamous cell carcinoma, adenocarcinoma, and large cell carcinoma. "In addition to HCC, Zbtb20 has also been proposed to have a high diagnostic value in the differential diagnosis between small-cell and non-small-cell carcinoma of the lung, most notably adenocarcinoma of the lung." (PMID 37762065, 2023).
osteoarthritis (1 paper, 2025). A noninflammatory degenerative joint disease occurring chiefly in older persons, characterized by degeneration of the articular cartilage, hypertrophy of bone at the margins and changes in the synovial membrane. "Thus, approaches inhibiting ZBTB20 activity emerge as promising treatments for osteoarthritis." (PMID 40069162, 2025). "Thus, according to current research, approaches suppressing ZBTB20 activity or expression will rescue the disturbed PTEN/PI3K-Akt signaling and alleviate OA symptoms, providing a promising lead for osteoarthritis treatment." (PMID 40069162, 2025).
osteoporosis (1 paper, 2022). A condition of reduced bone mass, with decreased cortical thickness and a decrease in the number and size of the trabeculae of cancellous bone (but normal chemical composition), resulting in increased fracture incidence. "Downregulation of ZBTB20 in chondrocytes slows down endochondral ossification, which is known to be impaired in osteoporosis." (PMID 36011354, 2022).
pituitary deficiency (1 paper, 2016). "Our identification of ZBTB20 as a crucial determinant of lactotrope specification provides insight into the ontogeny of lactotropes, which will help to unravel the cellular and molecular basis for pituitary deficiency." (PMID 27079169, 2016).
prostate adenocarcinoma (1 paper, 2023). "On the other hand, when we compared Prostate Adenocarcinoma (TGCA, PanCancer Atlas) dataset to that of our list of DEGs, we found IL6ST and ZBTB20." (PMID 37218885, 2023).